MGMT (O-6-methylguanine-DNA methyltransferase)
Diseases named in the same sentence as MGMT in open-access papers (continued):
Sharing a sentence is not in itself a finding about the gene and the disease.
glioma (continued). "However, the elevated expression of MGMT facilitates the removal of TMZ adducts, resulting in TMZ-resistant glioma cells." (PMID 41513607, 2026). "Noteworthy distinctions between gliomas with MGMT promoter methylation and those without were discerned for SImin (p = 0.019)." (PMID 41696572, 2026). "Subsequent tumor methylation profiling performed at the National Institutes of Health matched with high confidence to the class "IDH glioma, subclass astrocytoma" and confirmed lack of MGMT promoter hypermethylation." (PMID 41736408, 2026). "Further, amongst IDH1/2-wild-type tumors, where MGMT-methylation status is instrumental for therapeutic selection, almost a fifth of high-grade gliomas and more than 3-quarters of low-grade gliomas were not assessed for MGMT status." (PMID 39164213, 2025). "While some studies suggest ATRA might sensitize glioma cells to chemotherapy, the direct impact of ATRA on MGMT expression in conjunction with stemness marker reduction in GBM models enriched for stem-like properties remains a key area for investigation." (PMID 40422249, 2025). "Notably, G-CIMP-high tumors exhibit near-ubiquitous MGMT methylation, whereas MGMT methylation occurs sporadically in IDH-widetype/G-CIMP-negative gliomas." (PMID 40426960, 2025). "To evaluate the prognostic utility of combining PRRS with clinicopathological parameters, we constructed a nomogram based on WHO grade, age, 1p/19q codeletion status, MGMT promoter methylation status, and PRRS to predict the 1-, 3-, and 5-year survival rates of glioma patients." (PMID 41438761, 2025). "These gliomas almost universally have unmethylated O6-methylguanine-DNA-methyltransferase (MGMT) promoter and generally do not respond to the oral alkylating agent temozolomide (TMZ), with a dismal prognosis." (PMID 40697380, 2025). "Similarly, administration of the BAC regimen for patients with primary grade 4 gliomas was beneficial for those with IDH-wild-type and MGMT-unmethylated gliomas in terms of both OS and PRS, revealing substantial findings." (PMID 40746950, 2025). "We hypothesized that effects of imipridones on the ISR and global inhibition of protein translation might impact on MGMT expression and potential synergies when combined with TMZ for treatment of glioma cells." (PMID 40145650, 2025). "Unlike IDH wildtype glioblastoma, there is no clear response prediction with MGMT promoter methylation but it is associated with improved survival in IDH mutant gliomas." (PMID 40949165, 2025). "However, only 32% of patients with low-grade IDH1/2-mutant gliomas and 52% of patients with high-grade IDH1/2-mutant gliomas have been assessed for MGMT-methylation status." (PMID 39164213, 2025). "In our previous study, we found lower levels of immunosuppressive molecule sHLA-G in glioma patients with methylated MGMT compared with patients with a non-methylated MGMT promoter." (PMID 39796185, 2025). "Thus, MGMT KO in U1242 cells and MGMT KD in U1242, T98, and LN18 gliomas cells all decrease anchorage-independent clonogenicity in soft agar." (PMID 40336841, 2025). "In addition, a study revealed that receptor interacting protein 2 (RIP2) was upregulated in TMZ‐resistant glioma cells in correlation with drug resistance, and the RIP2/NF‐κB/MGMT signalling pathway plays a vital role in the regulation of TMZ resistance." (PMID 39873425, 2025). "Over half of the studies focused on high-grade gliomas (HGG), with 80% emphasizing MGMT prediction." (PMID 40218147, 2025). "We also found that PU-H71 downregulated EGFR and its downstream signaling pathway proteins, including AKT, S6, and MAPK, in glioma cells with and without MGMT methylation." (PMID 39682123, 2024). "In the present series, the MGMT promoter status was not a predictor of survival but a methylated status was frequently observed (72.5% of patients with grade 4 glioma), thus limiting the strength of the analysis regarding this parameter." (PMID 39456559, 2024).
glioma (continued). "Therefore, compounds able to enhance the TMZ response via downregulation of MGMT or ABCB1, and those able to reverse TMZ resistance or to target glioma stem cells, are intensively searched." (PMID 38611962, 2024). "In the present investigation, we found that PFS at first and second relapse was higher in patients with gliomas who had the methylated promoter of the gene that codes for MGMT protein compared to those who did not." (PMID 39767683, 2024). "EGFR amplification was also observed to be limited to IDH wildtype (26%) and TERT mutant (27%) gliomas, occurring irrespective of MGMT promoter methylation status and being mutually exclusive with 1p/19q co-deletion (LOH)." (PMID 38893240, 2024). "As the presence of the 1p/19q co-deletion and MGMT promoter methylation are indicative of the sensitivity of patients to TMZ, we investigated the value of the model in predicting TMZ sensitivity in patients with glioma." (PMID 39574472, 2024). "MGMT promoter methylation serves as a prognostic and predictive marker in GBM diagnosis, predicting the response to alkylating drugs like temozolomide (TMZ) in glioma patients." (PMID 38816839, 2024). "Radiomic models do not provide accurate predictions of the MGMT promoter methylation status in grade IV gliomas." (PMID 38308012, 2024). "In practice, the search for methylation of the MGMT gene only has prognostic value and does not predict response to treatment, so all patients with high-grade gliomas receive temozolomide." (PMID 39767683, 2024). "The 'proportion of non-enhancing 68–100%' feature presents an OR of 0.215 (p = 0.009) for being an MGMT-unmethylated glioma, implying that the larger the non-enhancing area, the greater the likelihood of the glioma being MGMT-methylated." (PMID 38167551, 2024). "It was found that circWDR62 was upregulated in both the TMZ-resistant glioma cells and TMZ-resistant glioma cell-derived exosomes, and that it promotes TMZ resistance and malignant glioma progression by targeting the miR-370-3p/MGMT axis." (PMID 38961907, 2024). "This analysis aimed to elucidate the molecular interactions of mucins with IDH1 and MGMT via EGFR, providing insights into their potential roles in glioma-related pathways and broader biological processes, and the resulting PPI enrichment p-value was <1.0 × 10−16, ranging from 0.99 to 0.42." (PMID 39767713, 2024). "Nevertheless, the non-trapping PARPi veliparib potentiated TMZ toxicity in MGMT-negative gliomas in vitro and in a mouse xenograft model." (PMID 39011394, 2024). "Indeed, pre‐existing heterozygous deletions encompassing MGMT, or an MMR gene had been observed in some gliomas which later developed hypermutated recurrence, highlighting the survival advantage of these two events." (PMID 38339779, 2024). "To the best of our understanding, no theory fully explains this phenomenon; however, we propose that gliomas with MGMT methylation tend to grow more slowly and stably, without a large necrotic area." (PMID 38167551, 2024). "Furthermore, MAN1C1 expression is elevated in glioma patients with wild-type IDH, 1p/19q co-deletion, and an unmethylated MGMT promoter status." (PMID 39333557, 2024). "A previous meta-analysis by Doniselli reported that radiomic models were not robust enough to accurately predict MGMT promoter methylation status in glioma patients before surgery with a pooled AUC of 0.78." (PMID 39594235, 2024).
glioma (continued). "In the TCGA glioma dataset, the high‐risk group had higher proportions of older, high‐grade, low KPS, IDH wild‐type, MGMT unmethylated, 1p/19q noncodel, mesenchymal, and IGS‐23 subtype patients (all p < 0.05)." (PMID 37545464, 2024). "In addition, we established a nomogram containing the prognostic factors, such as gender, MGMT status, IDH status, age, ARPC5 expression, 1p19q status, PRS, and grade, to forecast the possibility of 1-, 3-, and 5-year OS in glioma patients." (PMID 37789267, 2023). "In gliomas with MGMT-promoted methylation, MGMT is inactive and does not affect alkylating agents such as temozolomide." (PMID 37626776, 2023). "Moreover, studies revealed that DCE‐driven parameters were able to predict some of the molecular characteristics used recently for the classification of glioma tumors, including IDH and MGMT methylation." (PMID 36866773, 2023). "We stratified glioma patients into distinct subgroups based on gender, WHO grades, IDH status, 1p/19q status, MGMT promotor status, tumor stage, chemotherapy and radiotherapy, and observed the prognostic value of the reactive astrocyte score as a continuous variable in TCGA and CGGA datasets." (PMID 37416308, 2023). "Furthermore, most studies incompletely reported molecular information (IDH/MGMT) and were conducted prior to the changes in WHO glioma classification in 2021." (PMID 37733174, 2023). "Since infiltrative glioma samples are always an admixture of tumor and non-tumor cells, and MGMT testing is done on bulk tissue samples, an excess of non-tumor cells can mask a positive signal from glioma cells." (PMID 37919784, 2023). "In addition, stratified survival analysis was performed according to WHO grade, MGMT status, and age to assess the prognostic importance of LAIR‐1 in different subgroups of glioma patients." (PMID 35702880, 2023). "In addition, MGMT promoter unmethylation type shows a significantly higher expression of PTRF, indicating that higher PTRF expression is closely related to glioma ﻿temozolomide (TMZ) therapy resistance (p ≤ 6e-4)." (PMID 37322408, 2023). "In addition to IDH1/2 mutation, MGMT promotor methylation, EGFR amplification, TERT promotor mutation, and CDKN2A/B homozygous deletion, we sought to elucidate the alterations of other potential molecular biomarkers that might provide clues for clinical decision-making in gliomas." (PMID 36998447, 2023). "Paradoxically, TMZ did not appear to benefit patients with IDH-wildtype gliomas, regardless of MGMT promoter status." (PMID 37886555, 2023). "Therefore, the accurate diagnosis of the subtype of IHD mut combined with MGMT meth in glioma is of great value for the TMZ chemotherapy treatment decision and prognosis evaluation of gliomas." (PMID 36900232, 2023). "If MGMT genes are present in patients, the glioma will respond to chemoradiation with or without a diet intervention." (PMID 36960210, 2023). "1p/19q non-codel, IDH wild type, MGMT promotor unmethylated, plus CL and MES subtype and higher WHO grade are associated with poor outcomes of glioma." (PMID 37837543, 2023). "He underwent stereotactic biopsy and was diagnosed with IDH-wild-type, MGMT non-methylated glioma CNS WHO grade 3 (suggestive of PAA24) and was treated with radiochemotherapy with adjuvant temozolomide (TMZ)." (PMID 37287694, 2023). "Next, clinical data from glioma patients with concurrent MS were compared with data from control patients without MS and matched for tumor histology and the known prognostic markers IDH- and MGMT-status, age at diagnosis, and Karnofsky-Index." (PMID 38110626, 2023). "Using the supervised DNA methylation classification, transcriptional subtype, MGMT promoter status and TERT promoter status to color the adult gliomas from TCGA-LGG and TCGA-GBM also revealed distinct patterns across the adult glioma landscape." (PMID 36711972, 2023).
glioma (continued). "The expression levels of EMP3 and CHI3L1 in wild-type IDH-1, non-1P19Q co-deletion, and MGMT non-methylated gliomas were higher than in others." (PMID 37887529, 2023). "have discovered that if the MGMT promoter responsible for MGMT expression is methylated, then patients have higher chances of survival., Studies have shown that the MGMT signaling pathway also plays a role in the TMZ resistance of glioma tumor cells." (PMID 37182181, 2023). "We assessed the impact of ionizing radiation (2 Gy) on the intracellular delivery of 3′-carboxyfluorescein labeled nonspecific f-ON administered 1 day after radiation in MGMT-expressing T98G glioma cells in vitro." (PMID 33850305, 2022). "Our findings demonstrate that circWDR62 can be incorporated into exosomes and that exosomal circWDR62 might function as a miR-370-3p sponge to regulate MGMT, promoting the TMZ resistance and malignant development of glioma in vitro and in vivo." (PMID 35817771, 2022). "In different types and grades of gliomas, higher levels of IDH WT, MGMT promoter unmethylation, and 1p19q noncodeletion are more common in high-grade gliomas and the subtype of ME whose prognosis is worse." (PMID 36159780, 2022). "In addition, it has been reported that O6-methylguanine-DNA methyltransferase (MGMT) promoter methylation, which has been regarded as the indicator of temozolomide (TMZ) chemotherapy resistance, is also more likely to occur in glioma female patients." (PMID 35968285, 2022). "While PRRS increased as the stage advanced, higher PRRS was also observed in IDH1 wildtype, 1p/19q non-codeleted, and MGMT-promoter unmethylated gliomas compared to their counterparts." (PMID 35990696, 2022). "Moreover, increased CD146 expression correlated with higher glioma grades, IDH-wildtype status and unmethylated MGMT phenotypes." (PMID 35790583, 2022). "Conventional structural magnetic resonance imaging (MRI) features, including glioma location, glioma volume, necrosis, invasiveness, enhancement pattern, and peritumoral edema, have been used to predict the IDH, MGMT, and TERT status, however with controversies." (PMID 36471242, 2022). "Moreover, some years ago, it was reported that Wnt/β-catenin pathway regulates gene expression of the MGMT protein, directly leading to TMZ resistance in gliomas." (PMID 35626024, 2022). "The data revealed that the expression of LMO1 mRNA in human gliomas was correlated with 1p/19q co-deletion and MGMT promoter methylation status but not IDH status." (PMID 35280742, 2022). "In this manner, the MGMT methylation status was evaluated in 36 glioma patients and 3 negative control samples (meningioma, hemangiopericytoma, and peripheral blood leukocytes of a healthy individual)." (PMID 36361838, 2022). "In our studies, high ALKBH5 expression was associated with clinical features such as IDH wildtype status, 1p/19q non-codeleted status, and demethylation of MGMT, all of which were related to poor prognosis in the glioma patients." (PMID 35444654, 2022). "MGMT promoter methylation was predominant in Grade I, II and III gliomas." (PMID 36289655, 2022). "Methylation of MGMT promoter prevailed in II, III degree gliomas." (PMID 35625744, 2022). "High PLK4 expression was associated with clinical characteristic such as IDH wildtype status, 1p/19q non-codeleted status, and demethylation of MGMT, all of which were correlated with poor prognosis in patients with glioma." (PMID 36620611, 2022). "Indeed, IDH1-MUT and MGMT methylated tumors have significantly lower ITSS grades than IDH-WT and unmethylated MGMT gliomas." (PMID 36289752, 2022). "MGMT promotor methylation status was homogeneous in IDH-mutant glioma CNS WHO grade 2–3 (data not shown)." (PMID 35701666, 2022).
glioma (continued). "GSC gliomas showed significant heterogeneity and invasiveness on imaging, and exhibited strong expression of Ki-67, partial expression of EGFR and VEGF, and weak expression of MGMT and HIF-1α on immunohistochemical staining." (PMID 36591483, 2022). "It is known that the lack of comprehensive therapeutic effects of anti-glioma drugs is mediated in part by O6-methylguanine-DNA methyltransferase (MGMT)-mediated drug resistance." (PMID 36046834, 2022). "Integrated analysis of molecular key hallmarks in glioma (IDH, TERT, MGMT methylation, and LOH 1p/19q) and EGFR amplification showed that EGFR amplification is a phenomenon that can be predominantly found in IDH wildtype and TERT mutated gliomas, as well in gliomas without LOH 1p/19q." (PMID 35453544, 2022). "Five specific myeloid cell subtype gene signatures (MC2–MC5, and MC7) were independent prognostic indicators of glioma patient survival, independent of established covariates of glioma patient survival such as IDH mutation and MGMT methylation status." (PMID 36425564, 2022). "In the TCGA, CGGA, and CGGA (array) datasets, high angiogenesis pathway scores were enriched in the IDH wildtype, 1p19q non-codeleted, and MGMT promoter unmethylated gliomas." (PMID 35579998, 2022). "Firstly, our results indicated that PLVAP is related with IDH wild-type, non-codeleted 1p19q, unmethylated MGMT promoter, and mesenchyme subforms of gliomas, which was little known in previous researches." (PMID 36033326, 2022). "Evidence has shown that several molecules such as Ki-67, epidermal growth factor receptor (EGFR), vascular endothelial growth factor (VEGF), O-6-methylguanine-DNA methyltransferase (MGMT), and hypoxia-inducible factor 1-alpha (HIF-1α) play important roles in the growth of glioma." (PMID 36591483, 2022). "Interestingly, gene of MGMT was inversely correlated with ROCK2 expression in the recurrent group, especially in the recurrent glioma patient treated with TMZ or TMZ + radiation therapy." (PMID 35145081, 2022). "Patients in PLK1-high group had poorer prognosis compared to those in PLK1-low group both in MGMT promoter methylated and no-methylated glioma patients in CGGA-325, CGGA-693, and TCGA datasets." (PMID 36618405, 2022). "The risk scores of gliomas in GBM, age > 40, IDH wild-type, and 1p/19q noncodel and MGMT promoter unmethylated subtypes were significantly higher than those of the corresponding subtypes." (PMID 35592707, 2022). "MGMT, APNG, and ERCC1 mRNA were increased in microvesicles derived from glioma cells." (PMID 34687436, 2022). "In the current study, the gene microarray results showed that MGMT expression was not changed when glioma cells were cultured in gaMSC-conditioned media, so TMZ resistance was not related to MGMT expression and needs to be better understood." (PMID 34256854, 2021). "Comparison of DWI histogram profiles between high-grade gliomas with and without MGMT promotor methylation." (PMID 33857203, 2021). "With the exception of IDH-mutant gliomas, MGMT promoter methylation status did not correlate with other tested major glioma subtypes (ie, GBM-RTKII, GBM-mesenchymal, GBM-RTKI; not shown)." (PMID 33532726, 2021). "Gliomas with methylated MGMT promoters are more sensitive to TMZ-induced cytotoxicity with a longer median overall survival, as compared to patients whose tumors have unmethylated MGMT promoters." (PMID 33668200, 2021). "First, some clinical molecular features, such as O6-methylguanine (O6-MeG)-DNA methyltransferase (MGMT) status, which has been regarded as a robust predictor of prognosis in patients with glioma, were not included in the current analysis." (PMID 34123829, 2021). "Therefore, we included an extensive work up including the differentiation of high-grade versus low-grade gliomas and ATRX, IDH1/2, 1p19q, MGMT in our analysis." (PMID 34944806, 2021).